RNU6-355P (RNA, U6 small nuclear 355, pseudogene)
Gene: Small nuclear RNA gene on chromosome 16 (90,144,592 to 90,144,695, forward strand). Ensembl gene ENSG00000222359.
Homologues: Orthologues: macaque U6 (91% identical), pig U6 (84% identical), pig U6 (78% identical), dog U6 (77% identical). Paralogues in human: RNU6-1076P (100% identical), RNU6-1100P (100% identical), RNU6-1118P (100% identical), RNU6-1217P (100% identical), RNU6-447P (100% identical), RNU6-785P (100% identical), RNU6-791P (100% identical), RNU6-860P (100% identical), U6 (100% identical), RNU6-1054P (99% identical), RNU6-1199P (99% identical), RNU6-1319P (99% identical), and 1289 more.